ZNF30 (zinc finger protein 30)
Description:
May be involved in transcriptional regulation.
Synonyms: KOX28; DKFZp686N19164; FLJ20562
Tractability: PROTAC: ubiquitination databases record sites on it.
Gene: Protein-coding gene on chromosome 19 (34,926,887 to 34,945,172, forward strand). Ensembl gene ENSG00000168661.
Subcellular location: Nucleus
Subcellular location (Human Protein Atlas): Nucleoplasm; Cytosol
Pathways (Reactome):
Gene expression (Transcription): Generic Transcription Pathway; Regulation of endogenous retroelements by KRAB-ZFP proteins
Gene Ontology:
Molecular function: DNA-binding transcription factor activity, RNA polymerase II-specific; RNA polymerase II cis-regulatory region sequence-specific DNA binding
Biological process: regulation of transcription by RNA polymerase II; regulation of DNA-templated transcription
Cellular component: nucleus
Genetic constraint (gnomAD): Loss-of-function variants: 15 observed, 15.16 expected, observed/expected ratio (o/e) 0.99, 90% interval 0.66 to 1.52. The upper end of that interval is the gene's LOEUF score, 1.52, which puts it in group 6 of 6, group 1 being the genes least tolerant of losing a copy. Missense variants: 708 observed, 770.78 expected, observed/expected ratio (o/e) 0.92, 90% interval 0.86 to 0.98. Synonymous variants: 217 observed, 260.85 expected, observed/expected ratio (o/e) 0.83, 90% interval 0.74 to 0.93.
Homologues: Orthologues: chimpanzee ZNF30 (95% identical), macaque ZNF30 (92% identical). Paralogues in human: ZNF546 (56% identical), ZNF540 (54% identical), ZNF573 (51% identical), ZNF571 (49% identical), ZNF267 (47% identical), ZNF841 (47% identical), ZNF33B (46% identical), ZNF658 (46% identical), ZFP14 (46% identical), ZNF780B (45% identical), ZNF836 (45% identical), ZFP30 (45% identical), and 164 more.
Diseases named in the same sentence as ZNF30 in open-access papers:
ZNF30 is named in the same sentence as 4 diseases in open-access papers, as found by Europe PMC text mining. Sharing a sentence is not in itself a finding about the gene and the disease. The quoted sentences say what the papers report.
asthma (1 paper, 2018). "Using a mouse (Mus musculus) model of asthma applied to the Collaborative Cross population, we previously identified a lung gene expression quantitative trait locus (eQTL) for Zinc finger protein 30 (Zfp30) that was also a QTL for neutrophil recruitment and the hallmark neutrophil chemokine CXCL1." (PMID 29242385, 2018).
developmental delay (1 paper, 2024). "A microdeletion of five genes including ZNF30 results in chromosome 19q13.11 deletion syndrome that includes features such as: developmental delay, microcephaly and intellectual disabilities." (PMID 38177348, 2024).
ZNF30 also shares sentences with these, for which no sentence is quoted: intellectual disabilities (1 paper); microcephaly (1).